ALK (ALK receptor tyrosine kinase)
Diseases named in the same sentence as ALK in open-access papers (continued):
Sharing a sentence is not in itself a finding about the gene and the disease.
lymphoma (continued). "Zeng reported a CD30 aptamer-modified protamine nanomedicine containing a dsDNA/drug that effectively killed lymphoma cells as well as an ALK-specific siRNA, and importantly, the complex was virtually nontoxic to off-target cells." (PMID 36612296, 2023). "ALK- ALCLs represent a heterogeneous group of lymphomas with distinct clinical, immunophenotypic, and genetic features." (PMID 37810974, 2023). "The chimeric protein NPM::ALK functions as an oncogenic tyrosine kinase which impacts diverse cellular signaling pathways leading to lymphoma." (PMID 37810974, 2023). "When the CD30 marker shows a strong positive presence in nearly all lymphoma cells, the subsequent course of action involves assessing the level of ALK (CD246) expression." (PMID 38179383, 2023). "The mTOR pathway also acts as a bypass pathway of resistance and some investigators have shown a synergistic effect of combining ALK inhibitors with mTOR inhibitors in lymphoma cells." (PMID 37773318, 2023). "Genome-wide sequencing studies have shown that protein tyrosine phosphatases such as PTPN1 and PTPN2 are involved in ALK inhibitor resistance in lymphoma." (PMID 37773318, 2023). "Crizotinib, which is a novel small inhibitor of anaplastic lymphoma kinase (ALK) fusion protein, has been used in ALK-positive lymphomas, reducing toxicity and side effects." (PMID 35892871, 2022). "The existence of a chimeric ALK fusion protein plays a crucial role in the progression of these lymphomas." (PMID 35406421, 2022). "To date, few entities such as ALK+ ALCL or T-PLL display specific genetic aberrancies that are the predominant driving force of lymphoma progression and therefore constitute a distinctive feature for classification." (PMID 36605429, 2022). "A review of over 30,000 tumors excluding those with NSCLC or lymphoma from two of these commercial vendors identified ALK rearrangements in 1/1,000 specimens and ROS1 rearrangements in 4/10,000 specimens." (PMID 35233056, 2022). "The combination of chemotherapy and ALK DNA vaccination significantly enhances the survival of mice challenged with ALK+ lymphomas." (PMID 35958559, 2022). "In other models of cholesterol auxotrophy, which include ALK+ lymphomas and renal cell carcinomas, the phenotype was driven by low expression or mutations in key cholesterol biosynthesis genes." (PMID 35884604, 2022). "Because ALK was initially discovered and characterized in a rare type of lymphoma called anaplastic large-cell lymphoma (ALCL) as an NPM-ALK fusion protein, ALK mutation and overexpression have been found in many cancer types." (PMID 35508387, 2022). "Overall, we have established a unique efficient genome-editing strategy to model gene fusions in primary human lymphocytes and characterized the steps of normal T-cell progression into transformed ALK+ lymphomas in vivo." (PMID 35246138, 2022). "In an expanded molecular cohort of subjects compiled by three commercial vendors, the detection of ALK or ROS1 rearrangements outside of NSCLC or lymphoma was rare." (PMID 35233056, 2022). "Unfortunately, patients with ALK-positive lymphoma who stopped taking crizotinib experienced a sudden relapse." (PMID 35406421, 2022). "All of the mutant translocations result in constitutive ALK-tyrosine kinase activation, which is an important change in this lymphoma." (PMID 35406421, 2022). "Different from ALK+ALCL and ALK−ALCL, primary cutaneous ALCL and-breast implant-associated ALCL are far less aggressive lymphomas presenting only one or very few sites." (PMID 35406421, 2022). "WT1 has been reported to be expressed in acute leukemias and in several lymphomas, including ALK+ sALCLs (3/6, 50%), ALK− sALCLs (14/31, 45%) and cALCLs (1/6, 17%)." (PMID 34944796, 2021). "The fused protein between ATIC and anaplasia lymphoma kinase (ALK, a common oncogene) was discovered in lymphoma patients." (PMID 34650911, 2021). "NCT02419287 studies the effects of Crizotinib alone on relapsed ALK(+) lymphomas in an adult population." (PMID 33466277, 2021).
lymphoma (continued). "We currently apply this method in clinical routine to identify routes of resistance to ALK inhibitors in ALK+ lymphoma patients, including B-cell cases (Mologni, unpublished data)." (PMID 34680298, 2021). "This lymphoma is defined as the involvement of the lymph nodes, bone marrow, and/or extranodal organs by ALK- ALCL at initial presentation." (PMID 34572893, 2021). "Recent molecular studies have identified diverse genetic alterations in ALK- ALCL that convey different prognoses and have different underlying pathogenetic mechanisms, obviating the heterogeneity of this group of lymphomas." (PMID 34572893, 2021). "This is an important prerequisite to identify potential therapeutic targets in ALK+ lymphoma and to gain a deeper understanding of large-scale epigenetic rearrangements that drive tumor transformation in general." (PMID 33310759, 2021). "In our results, some of the differentially methylated genes in EHMT2 + MCL cases have also been reported with recurrent genetic alterations in lymphoma, such as ALK, DUSP22, NCOR2, RORA, DLC1, JAG1/2, JAK1, NOTCH4, and CD1938–45." (PMID 34633777, 2021). "In NSCLC with ALK rearrangements, the ALK protein is expressed at levels much lower than that in lymphomas with ALK rearrangements." (PMID 34066104, 2021). "ALK fusions have been identified in a variety of neoplasms, including inflammatory myofibroblastic tumor, many subtypes of lymphomas and leukemias, adenocarcinomas, benign fibrous histiocytoma, and several other tumors." (PMID 34745213, 2021). "Such an assembly was proven to selectively bind lymphoma cells, deliver the siRNA intracellularly, silence ALK expression, and arrest the growth of lymphoma cells." (PMID 33777893, 2021). "Combinations with BCR-ABL inhibitors against lymphoma cell lines and with ALK inhibitors against NSCLC cell lines were desirable, wherein all the drug–cell line pairs exhibited synergistic effects." (PMID 33758275, 2021). "For precision therapy, we report herein a protamine nanomedicine incorporated with oligonucleotide aptamers to selectively target lymphoma cells, a dsDNA/drug payload to efficiently kill targeted cells, and an siRNA to specifically silence ALK oncogenes." (PMID 32218299, 2020). "The prediction of high synergy between the first-generation inhibitors of ALK and proteasome for lymphoma cell lines highlights the potential of comboFM to predict biologically plausible combination effects." (PMID 33262326, 2020). "Another fusion between ALK and tropomyosin (TPM) with similar effect as the ALK-NPM fusion has also been described in lymphomas." (PMID 32283832, 2020). "To investigate precision ALCL treatment, we utilized the facts that lymphoma cells aberrantly express high levels of surface CD30 and have an active pathogenic ALK oncogene due to abnormal chromosomal translocation." (PMID 32218299, 2020). "For instance, we confirm a novel synergy between anaplastic lymphoma kinase (ALK) inhibitor crizotinib and proteasome inhibitor bortezomib in lymphoma cells." (PMID 33262326, 2020). "Simultaneously, macropinocytosis of the protamine nanomedicine by the targeted cells will lead to the intracellular delivery of intact siRNA to silence ALK oncogenes and inhibit lymphoma cell proliferation." (PMID 32218299, 2020). "ALK+ ALCL is typically a nodal lymphoma (90% of cases), while extranodal involvement is observed in 60% of cases." (PMID 33261174, 2020). "ALK+ LBCL is an ALK-positive lymphoma with a plasma cell-like immunophenotype, accounting for less than 1% of all cases of DLBCLs." (PMID 33261174, 2020). "Of note, in ALK+ ALCL they have pro-oncogenic functions because ALK promotes lymphoma cell proliferation and survival by increasing their GTPase activity through the direct phosphorylation of their RHO GEFs VAV1/VAV3." (PMID 31248017, 2019). "In ALK+ ALCL the ALK-dependent downregulation of WASP contributes to the lymphoma proliferation/survival by increasing active CDC42 and MAPK pathway." (PMID 31248017, 2019).
lymphoma (continued). "All the variant translocations lead to the constitutive activation of ALK-tyrosine kinase and represent the critical alteration in this lymphoma." (PMID 29617304, 2018). "The biology of ALK is best characterised in lymphoma cells expressing the NPM-ALK fusion oncoprotein." (PMID 29642598, 2018). "BALB/c mice were vaccinated with plasmids encoding for the cytoplasmic portions of ALK and subsequently challenged with ALK-positive lymphoma cells." (PMID 29642597, 2018). "Elevated expression and/or the constitutive activation of c-Jun and JunB are common to other CD30–positive lymphomas including ALK+ ALCL19,20,22,23, ALK− ALCL20,24, cutaneous ALCL20,24,25, and CD30–positive diffuse large B cell lymphoma." (PMID 30375407, 2018). "The immunization led to a long-lasting local and systemic lymphoma protection in ALK-vaccinated mice." (PMID 29642597, 2018). "Successful applications of the drug on the target protein/gene in ALK rearrangement- positive lymphoma have also been reported." (PMID 27974674, 2017). "IHC is a relatively inexpensive method for diagnosing ALK rearranged lymphoma that, like FISH, requires biopsy sample." (PMID 27974674, 2017). "Significant ALK kinase domain RNA expression was observed in ALK rearrangement-positive lymphoma cells." (PMID 27974674, 2017). "A combination of chemotherapy and vaccination significantly enhanced the survival of mice challenged with ALK+ lymphomas." (PMID 29189709, 2017). "Functional chimeric proteins formed by fusing ALK with other proteins have found in many lymphoma subtypes, including anaplastic large-cell lymphoma (ALCL) and diffuse large B-cell lymphoma (DLBCL)." (PMID 27974674, 2017). "HMGB-1 in turn promotes the secretion of IL-8 and MMP-9 by keratinocytes, which result in epidermal inflammation and the invasiveness of ALK+ lymphoma cells, respectively." (PMID 28895885, 2017). "Targeted therapies for ALK-positive lymphoma will thus require development of second generation small molecule inhibitors or combination therapies to prevent treatment failure." (PMID 28895885, 2017). "It was demonstrated that these lymphomas display activation of ALK signalling pathways and are potently suppressed in vitro and in vivo by a selective ALK inhibitor." (PMID 28665943, 2017). "We characterized the expression of sweyjawbu in a number of lymphoma cell lines in order to evaluate its usefulness as a predictor of ALK rearrangement status." (PMID 27974674, 2017). "The existing approach for detecting endogenous antibodies against ALK in lymphoma patients is based on a semi-quantitative immunocytochemical technique." (PMID 29190913, 2017). "Comparable results were observed from PCR assay and IHC or FISH tests, to determine ALK rearrangement status in lymphomas." (PMID 27974674, 2017). "We further confirmed that these autoantibodies were specific for the ALK intracellular domain using Western blots with lymphoma cells where the expression of the endogenous NPM-ALK was knocked down with a doxycycline-inducible ALK shRNA." (PMID 29190913, 2017). "First, as we showed in this study, ALK is a natural shared antigen in NSCLC patients, consistent with previous reports in ALK-positive lymphoma patients." (PMID 29190913, 2017). "ALK-positive lymphoma cells have been shown to release the pro-inflammatory cytokine high-mobility-group box-1 (HMGB-1), which is thought to promote the creation of a “premetastatic niche” within the skin." (PMID 28895885, 2017). "This review discusses the role of miRNA and DNA methylation in drug resistance mechanisms and highlights their potential as anti-cancer therapies in Anaplastic Lymphoma Kinase (ALK)-positive lymphomas." (PMID 28771164, 2017). "Both ALK+ and ALK− lymphomas are classified, together with AITL and PTCL-NOS, as peripheral T cell lymphomas, which have–in contrast to, e.g., lymphoblastic lymphoma–by definition a post-thymic origin." (PMID 27705804, 2016).
lymphoma (continued). "We observed a specific synergistic effect of combining ALK inhibitors with an mTOR inhibitor (temsirolimus), in ALK+ lymphoma cells." (PMID 27662658, 2016). "Although the significance of the biological regulation of the ALK activation pathway is yet to be established, these lines of evidence highlight their importance in lymphoma and immunity." (PMID 27598116, 2016). "In a small study consisting of 11 patients with refractory ALK-positive lymphoma, nine had ALCL histology." (PMID 27071634, 2016). "Crizotinib exerted potent antitumor activity in advanced ALK-positive lymphoma patients; a clinical trial evaluating crizotinib in patients with primary ALK-positive systemic ALCL is ongoing (NCT02487316)." (PMID 27071634, 2016). "Non-allele-specific ALK RT-qPCR revealed ALK overexpression and 5′ RACE PCR revealed that the patient’s lymphoma expressed a TRAF1-ALK fusion." (PMID 26187744, 2015). "Several distinct, non-NPM1, ALK fusions have subsequently been described in lymphomas and other tumor types." (PMID 26187744, 2015). "One key factor likely impacting favourable prognosis in this lymphoma is the relatively young age (average age of 16–22) of ALK+ ALCL patients." (PMID 25168906, 2014). "The expression of ALK in this lymphoma occurs secondary to one of several chromosomal aberrations that involve the ALK gene on chromosome 2p23." (PMID 25026277, 2014). "Lymphoma cells typically possess T cell receptor gene rearrangements; however, the expression of many T cell markers is variable in ALK+ ALCL." (PMID 25168906, 2014). "24–25 Other potential differential diagnoses include CD20-negative aggressive lymphomas such as solid or extracavitary primary effusion lymphoma and ALK+ DLBCL." (PMID 25408850, 2014). "Our findings reveal that GzB expression is more than just a phenotypic characteristic of ALK+ ALCL lymphoma cells, as expression of this serine protease sensitizes ALK+ ALCL tumour cells to drug-induced apoptosis." (PMID 25168906, 2014). "NPM-ALK signals in part through Rac1 thereby contributing to the pathogenesis of ALK-positive human lymphomas." (PMID 23874639, 2013). "The activation of GLI1 transcription factor by ALK was reported in a lymphoma cell line and was ascribed to signaling through PI3/Akt." (PMID 24163262, 2013). "In ALK+ ALCL, the activation of STAT3 has been strongly implicated in the pathogenesis of this lymphoma." (PMID 22852078, 2012). "Encouraging initial clinical results with the anaplastic lymphoma kinase (ALK) inhibitor crizotinib in advanced chemoresistant ALK+ lymphoma patients have also been observed." (PMID 22536253, 2012). "In our study, we retrospectively analyzed 92 patients with S-ALCL from the Peking University Lymphoma Center for clinical and molecular prognostic factors to make clear the role of ALK and other prognostic factors in Han Chinese S-ALCL." (PMID 22769020, 2012). "Its key involvement in lymphoma suggests a role in the immune network although the function of the normal ALK protein is poorly understood." (PMID 22254144, 2011). "In fact, IL-9 transgenic mice transplanted with NPM-ALK-transfected BM cells developed not only ALK+ lymphomas, but also various types of benign and malignant MC lesions." (PMID 21297223, 2010). "Lymphoma cells also expressed the ALK protein in all NPM-ALK mice analyzed, whereas the unaffected tissues in these animals were found to be ALK-negative." (PMID 21297223, 2010). "A remarkable aspect is that CD30 is primarily detectable in advanced SM, and that this antigen (Ki-1) is otherwise also expressed in NPM/ALK+ lymphomas." (PMID 21297223, 2010). "Usually, ALK+ lymphoma is very sensitive to chemotherapy; thus, if the diagnosis is made without the need for thoracotomy and resection, chemoradiotherapy may be sufficient." (PMID 39980557, 2025). "The CHOEP (CHOP + etoposide) regimen is preferred in younger patients with ALK-positive lymphoma." (PMID 41346922, 2025).
lymphoma (continued). "For our Case 1, given the diffuse EBV positivity observed in lymphoma cells, we did not pursue further molecular genetic studies for the diagnostic possibility of ALK-negative ALCL." (PMID 38921179, 2024). "ALK inhibition already has, or could be, combined with either standard chemotherapy, CD30 antibody-toxin conjugate, or, preferably, agents targeting pathways playing a role in ALK-driven lymphomas." (PMID 38638855, 2024). "In lymphoma research, the utilization of antibody reactions primarily involves the detection of ALK antibody titers in peripheral blood and/or bone marrow samples of ALK-positive ALCL patients." (PMID 38365716, 2024). "The ALK-high group revealed up-regulated pathways involved in cell cycle and cancer proliferation, which recapitulates an accelerated tumorigenesis observed in a chromosome instability induced aneuploidy lymphoma model." (PMID 38585847, 2024). "Indeed, in ALK-positive lymphoma sensitive cell lines (K299, SUP-M2), previous 20 h exposure to crizotinib or lorlatinib (i.e., 0.5 μM and 0.1 μM, respectively) induced increased phagocytosis with anti-CD47 mAb." (PMID 39767726, 2024). "Interim PET was predictive of outcome in all lymphoma entities except ALK-positive ALCL." (PMID 40453056, 2024). "Interestingly, dual inhibition of SHP2 and ALK has been shown to be an effective approach for ALK-translocated lung tumors and lymphomas that are resistant to ALK inhibitors, suggesting potential benefits of combining ALK and SHP2 inhibitors." (PMID 38032104, 2023). "Interestingly, we found that STAT3 binds to super-enhancers that regulate high expression of Bcl-xL in both ALK+ and ALK− ALCL lymphoma cell lines." (PMID 36045346, 2022). "ALK was recognized as an oncogenic driver in lymphoma and some solid tumors." (PMID 35327685, 2022). "Moreover, vaccination of mice with ceritinib-treated ALK-dependent ALCL was able to restrain the progression of the same lymphoma inoculated 2 weeks later." (PMID 34272360, 2021). "ALK-positive LBCL is a high-grade lymphoma usually involving lymph nodes and mediastinum, although extra-nodal sites may be involved." (PMID 34572754, 2021). "Cytogenetic studies performed in BIA-ALCL cell lines (TLBR-1, TLBR-2, and TLBR-3) have shown a complex karyotype and the absence of chromosomal abnormalities associated with other lymphomas, including systemic ALK- ALCL and pc-ALCL." (PMID 34572893, 2021). "The immunophenotype of the lymphoma cells is identical to ALK- ALCL and pc ALCL." (PMID 34572893, 2021). "In addition, anaplastic lymphoma kinase (ALK) positive lymphoma cells can shift the cholesterol synthesis to squalene formation, thereby counteracting lipid peroxidation and ferroptosis." (PMID 33891303, 2021). "Systemic ALK-positive ALCL (ALK+ ALCL), associated with translocation of the anaplastic lymphoma kinase (ALK) oncogene, has been considered a distinct entity since the WHO revised lymphoma classification in 2016." (PMID 34685497, 2021). "In addition to the known chemo- and targeted-therapies, immunotherapies are now studied as part of the drug arsenal against ALK+ lymphoma." (PMID 34685497, 2021). "In ALCL, combination of chemotherapy and ALK DNA vaccine could also prevent in vivo tumor growth and increased survival of lymphoma-bearing mice." (PMID 32059449, 2020). "Moreover, because of acquired resistance from first- and second-generation agents, a phase 2 study (NCT03505554) to define the ORR of lorlatinib in patients with ALK+ lymphomas resistant or refractory to ALK inhibitors is ongoing." (PMID 32296035, 2020). "We thus used RNA-based CD30-specific aptamers for selective cell targeting, an ALK oncogene-specific siRNA for gene therapy, and the chemotherapeutic drug doxorubicin (Dox) in a DNA intercalation form to kill targeted lymphoma cells, as described in the Materials and Methods Section." (PMID 32218299, 2020).